RAD51C (RAD51 paralog C)
Diseases named in the same sentence as RAD51C in open-access papers (continued):
Sharing a sentence is not in itself a finding about the gene and the disease.
breast cancer (continued). "Nor was it large enough to address the variant detection rates for the ovarian susceptibility genes RAD51C and RAD51D that have previously been excluded as breast cancer susceptibility genes, but which were more recently confirmed as breast cancer genes just reaching two-fold relative risk." (PMID 34439310, 2021). "Moreover, individuals with pathogenic RAD51C variants are not candidates for increased breast surveillance or prophylactic surgical interventions because there is no indication of an elevated risk of BC, with the exception of triple negative breast cancer." (PMID 31782267, 2020). "This is consistent with previous reports in breast cancer and cell line experiments where Signature 3 was only detected for BRCA1/2, PALB2 and RAD51C genes but not ATM or CHEK2." (PMID 33917078, 2021). "Thus, BRCA1 and RAD51C promoter methylation, likely in combination with LOH, may have led to the HRD phenotype for a sizable portion of the ovarian and of breast cancer patients with no clear biallelic loss of the HRD associated genes, and potentially for patients with other cancer types as well." (PMID 33149131, 2020).
Fanconi anemia (51 papers, 2011 to 2024). Fanconi anemia (FA) is a hereditary DNA repair disorder characterized by progressive pancytopenia with bone marrow failure, variable congenital malformations and predisposition to develop hematological or solid tumors. "Biallelic inactivation of BRCA2 (FANCD1) or RAD51C (FANCO) also causes Fanconi anemia (FA), an autosomal recessive disorder due to pathogenic mutations in one of twenty-three identified FANC genes." (PMID 36906610, 2023). "Severe sensitivity to crosslinking agents is a defining feature of cells derived from Fanconi anemia (FA) patients and unsurprisingly, RAD51C (FANCO) and XRCC2 (FANCU) mutations have been uncovered in FA or FA-like patients." (PMID 30551670, 2018). "Functional alterations in Rad51C are the cause of the Fanconi anemia complementation group O (FANCO) gene disorder." (PMID 25669972, 2015). "At the same time, a biallelic mutation in RAD51C was reported in a family with multiple severe abnormalities characteristic of Fanconi Anemia." (PMID 21980511, 2011). "Likewise, bi-allelic RAD51C (or FANCO) deleterious variants have been found in Fanconi Anemia patients." (PMID 33333735, 2020). "One patient (12U) with multiple congenital malformations was found to have compound heterozygous variants in RAD51C, a gene associated with Fanconi anemia, a mosaic VOUS in ENG, and seven additional mosaic variants in genes with no definitive disease association." (PMID 31349857, 2019). "Likewise, biallelic BRCA1, BRCA2, BRIP1, PALB2 and RAD51C mutations lead to Fanconi anemia." (PMID 36292468, 2022). "Approximately half of high-grade serous epithelial ovarian cancers incur alterations in genes of homologous recombination (BRCA1, BRCA2, RAD51C, Fanconi anemia genes), and the rest incur alterations in other DNA repair pathways at high frequencies." (PMID 37684587, 2023). "The Cancer Genome Atlas (TCGA) analysis reported that HGSC tumors are characterized by mutations in PTEN (7%), RAD51C (3%), ATM/ATR (2%) and Fanconi anemia genes (5%)." (PMID 36531003, 2022). "BRCA1 and BRCA2 are part of the BRCA–Fanconi anemia pathway, and other Fanconi genes, such as BRIP1 and RAD51C, have also been associated with an inherited risk of OC." (PMID 36555431, 2022). "Another interesting finding in our cohort is the high incidence of monoallelic variants in other Fanconi anemia (FA) genes: FANCA, FANCC, FANCD2, RAD51C, FANCG and FANCI." (PMID 36290365, 2022). "As RAD51C is a Fanconi anemia gene (FANCO; OMIM # 613390), the NCCN clinical practice guidelines in oncology recommend counseling RAD51C GPV carriers about the risk of autosomal recessive conditions in their offspring." (PMID 36233090, 2022). "Most detected variants affected the Fanconi anemia/DNA repair pathway (34%, ATM, FANCA, FANCI, MLH1, MSH6, POLE, RAD51C, RAD51D) followed by mutations altering the SWI/SNF (SWItch/sucrose non-fermentable) complex (22%, ARID1A and SMARCA4)." (PMID 34200508, 2021). "Overall, 14.6% had mutations in BRCA1 or BRCA2, 3.3% had mutations in other BRCA–Fanconi anemia genes (BRIP1, PALB2, RAD51C, RAD51D, BARD1), and 0.4% had mutations in mismatch repair genes linked to Lynch syndrome." (PMID 32679669, 2020). "Mutations in RAD51C and XRCC2 result in Fanconi anemia, a syndrome associated with extreme sensitivity to drugs like mitomycin C (MMC) that induce DNA interstrand crosslinks." (PMID 31584931, 2019). "Deficiency in several of the classical human RAD51 paralogs [RAD51B, RAD51C, RAD51D, XRCC2 and XRCC3] is associated with cancer predisposition and Fanconi anemia." (PMID 31584931, 2019). "Initial studies reported the RAD51C gene (MIM:602774) as another Fanconi anemia (FA) gene designated as FANCO because its biallelic germline mutations were found in a patient with FA-like phenotype corresponding to complementation group O." (PMID 26057125, 2015).
Fanconi anemia (continued). "Our studies show that genes like ATM, ATRX, RAD51C, along with members of the Fanconi Anemia pathway (FANC-B, C, E, I, L, and M), and SETD2, the methyltransferase regulating H3K36me3, were all associated with the combination of H3K36me3, γH2AX and enhanced R-loops." (PMID 39178326, 2024). "FANCS/BRCA1, FANCD1/BRCA2, FANCN/PALB2 and FANCO/RAD51C are Fanconi anemia (FA) genes." (PMID 37566130, 2023). "Interestingly, germline mutation rate of members of the Fanconi anaemia family of genes (including BRCA2, PALB2, BRIP1, RAD51C, FANCA, FANCI and FANCL) was 53.4% (31/58) among the patients with germline mutations in our cohort." (PMID 32091409, 2020). "Monoallelic germline pathogenic variants (GPVs) in five Fanconi anemia (FA) genes (BRCA1/FANCS, BRCA2/FANCD1, PALB2/FANCN, BRIP1/FANCJ, and RAD51C/FANCO) confer an increased risk of breast (BC) and/or ovarian (OC) cancer, but the role of GPVs in 17 other FA genes remains unclear." (PMID 39149814, 2024). "Although they mainly affect the BRCA1 and BRCA2 genes, they have been detected in other genes such as RAD51C hypermethylation (RAD51 paralog C), ATM (ataxia telangiectasia mutated serine-protein kinase gene), or ATR mutations, and mutations of the HR interacting Fanconi anemia gene." (PMID 34638899, 2021). "After discovering that it was associated with Fanconi anemia, they screened for mutations in RAD51C in 1100 hereditary breast (HBC) and HBOC families, hypothesizing that it would be similar to BRIP1 and BRCA2 in which biallelic mutations cause Fanconi anemia and monoallelic mutations cause HBOC." (PMID 21980511, 2011). "HRR alterations involve Fanconi anemia genes (PALB2, FANCA, FANCL, FANCI, FANCC), core RAD genes (RAD50, RAD51, RAD51B, RAD51C) as well as DNA damage response genes (ATM, ATR, CHEK1, CHEK2)." (PMID 36531003, 2022). "Additionally, we found 7 monoallelic pathogenic variants (2%, 7/327) in 6 genes (besides BRCA1/2) of the interstrand crosslink DNA repair Fanconi anemia pathway (FANCB, FANCC, FANCF, FANCI, FANCL, FANCM) and 1 in RAD51C, a Fanconi-like phenotype gene." (PMID 30262796, 2018). "These genes include the Fanconi anemia pathway genes: FANCA, PALB2, BRIP1, RAD51C and XRCC2 and non-Fanconi anemia genes: ATM, CHEK2, NBN, RAD50, RAD51B, and RAD51D." (PMID 28202063, 2017).
prostate carcinoma (21 papers, 2012 to 2025). A carcinoma that arises from epithelial cells of the prostate gland. "To study the role of RAD51C mutations in other common cancer types, we genotyped the Finnish RAD51C founder mutations c.837 + 1G > A and c.93delG in 1083 prostate cancer patients and 802 colorectal cancer patients using TaqMan Real-Time PCR." (PMID 23176254, 2012). "RAD51C is an enigmatic predisposition gene for breast, ovarian, and prostate cancer." (PMID 37488098, 2023). "This clinical trial will include advanced/relapsed ovarian, breast, pancreatic, and prostate cancer patients who can be treated with PARPis and HER2-negative breast cancer patients with BRCA1/2, PALB2, RAD51C, and RAD51D mutations." (PMID 40521389, 2025). "Soon afterwards, the FDA granted further approval for the application of talazoparib in the treatment of prostate cancer patients exhibiting mutations in HRR pathway genes, encompassing CDK12 and RAD51C (Akbıyık and Ürün, 2023)." (PMID 38953104, 2024). "It has been revealed that DDR genes alterations including BRCA2, BRCA1, CDK12, ATM, FANCD2, or RAD51C affect almost 20% of 333 primary prostate cancer." (PMID 36739400, 2023). "For likely pathogenic mutations, FANCM and FH ranked top for kidney cancer, RAD51C ranked top for bladder cancer, and ATM and PMS2 ranked top for prostate cancer." (PMID 36451132, 2022). "BRCA2-type HRD deficiencies (including BRCA2, RAD51C, PALB2 deficiencies) were more frequent in pancreatic and prostate cancer." (PMID 33149131, 2020). "RAD51C c.1026+5_1026+7delGTA was identified in P-69, diagnosed with OC at age 52 and the family history included BC, OC and prostate cancer." (PMID 31882575, 2019). "In breast, ovarian, pancreatic, and prostate cancers, homologous recombination (HR)–deficiency signatures were more common in tumors with new pathogenic missense mutations in BRCA1/2, PALB2, and RAD51C than in benign missense mutations (66.7% v 35.2%, P = .021)." (PMID 40570257, 2025). "Moreover, there is good evidence from prostate cancer that the PARPi olaparib is effective in tumours with alterations in RAD51C, RAD51D, CHEK2, PALB2, RAD54L, and BARD1." (PMID 34680387, 2021). "Among the 504 non-prostate cancer cases diagnosed at our institution with the same NGS approach, three carriers of the same mutations were found, one with the FANCD2 mutation and two with the RAD51C mutation, with different cancers occurring in the families." (PMID 29659569, 2018). "In a molecular analysis of 333 primary prostate cancers, the Cancer Genome Atlas (TCGA) study showed a 19% prevalence of alterations in several DNA repair genes, including BRCA2, BRCA1, ATM, CDK12, FANCD2, and RAD51C." (PMID 37240284, 2023). "In several tumor types, particularly breast, ovarian, pancreatic, and prostate cancers, a strong correlation was observed between increased gLOH and biallelic alterations in other HR genes beyond BRCA1 and BRCA2, including BARD1, PALB2, FANCC, RAD51C, and RAD51D." (PMID 37761329, 2023).
Lynch syndrome (19 papers, 2017 to 2025). An autosomal dominant hereditary neoplastic syndrome characterized by the development of colorectal carcinoma and a high risk of developing endometrial carcinoma, gastric carcinoma, ovarian carcinoma, renal pelvis carcinoma, and small intestinal carcinoma. "Mutations in BRCA1/2, RAD51C/D, and Lynch syndrome genes were associated with a high OC risk, while mutations in BRIP1 were associated with a moderate OC risk in our study, in concordance with previous reports." (PMID 32295079, 2020). "A high OC risk has also been associated with germline mutations in RAD51C, RAD51D, Lynch syndrome genes, and STK11; a moderate OC risk with BRIP1." (PMID 32295079, 2020). "This mutation was found in the patient carrying also the truncating mutation in RAD51C (HPC186) and is classified as pathogenic in two of the Lynch syndrome families diagnosed at IPO Porto." (PMID 29659569, 2018). "The most significant risk factor for OC development are germline pathogenic/likely pathogenic variants (GPVs) in OC predisposition genes (including BRCA1, BRCA2, BRIP1, RAD51C, RAD51D, Lynch syndrome genes, or BRIP1), which contribute to the development of over 20% of all OC cases." (PMID 38069345, 2023). "Of these, five mutations (9.26%, 5/54) were in homologous recombination repair (HRR) pathway genes, including PALB2 (1.85%, 1/54), BLM (1.85%, 1/54), NBN (1.85%, 1/54), RAD51C (1.85%, 1/54), and RAD51D (1.85%, 1/54), and one mutation was in MSH3 (1.85%, 1/54) related to Lynch syndrome." (PMID 33194720, 2020). "Furthermore, a combined 27% of participants who had genetic testing reported a mutation in BRCA1 (12%), BRCA2 (7%) or in another OC gene (8%; most commonly RAD51C/D, CHEK2 and the Lynch Syndrome genes)." (PMID 35621661, 2022). "In addition to RAD51C, RAD51D and BRIP1 genes, it would be appropriate for an OC panel to also include PALB2 and Lynch Syndrome genes going forward." (PMID 34503154, 2021).
breast and ovarian cancer (12 papers, 2011 to 2026). "Most familial pancreatic cancer is attributable to hereditary breast and ovarian cancer syndrome that results from germline mutations in BRCA1/2 genes and other genes such as ATM, BRIP1, CHEK2, RAD50, and RAD51C." (PMID 38732320, 2024).
pancreatic cancer (12 papers, 2020 to 2024). "MGPTs generally cover at least 10 common HR-related genes such as ATM, BARD1, BRCA1, BRCA2, BRIP1, CHEK2, NBS1 (NBN), PALB2, RAD51C, and RAD51D, all of whose germline alterations are associated with BRCAness phenotypes for predisposition to breast, ovarian, prostate, or pancreatic cancer." (PMID 35008774, 2021). "Except for MSH3, the rest of the germline mutant genes in non-BRCA carriers with TNBC were involved in the HRR pathway, including BLM, PALB2, NBN, RAD51C, and RAD51D, with the mutation rate of 9.26% (5/54), which increased the risk of other cancers, such as PLAB2 for pancreatic cancer." (PMID 33194720, 2020).
triple-negative breast carcinoma (11 papers, 2016 to 2025). An invasive breast carcinoma which is negative for expression of estrogen receptor (ER), progesterone receptor (PR), and human epidermal growth factor receptor 2 (HER2). "The RAD51C c.905-2A>G is a splice acceptor variant, considered to be likely pathogenic, and it was confirmed in a triple-negative breast cancer patient who also had a VUS in the MUTYH gene (c.536A>G)." (PMID 40508121, 2025). "Pathogenic RAD51C variants have previously also been linked particularly to ER-negative and triple-negative breast cancer subtypes, but all six identified carriers from the unselected cohort turned out to be ER- and PR-positive." (PMID 37578974, 2023). "This study and others, have also demonstrated that carriers of pathogenic RAD51C/D mutations tend to develop triple-negative breast cancers, in contrast to the predominantly (4 of 5 cases) hormone receptor-positive breast cancers identified among carriers of RAD51B mutations in our cohort." (PMID 34635660, 2021). "Out of the genes that have a role in the BRCA1/2 HR pathway, NCCN Guidelines (version 2.2021) indicate that the risk of triple negative breast cancer is potentially increased in patients with P/LP variants in BRIP1, RAD51C and RAD51D." (PMID 35710434, 2022). "Pathogenic germline mutations in the RAD51 paralog genes RAD51C and RAD51D, are known to confer susceptibility to ovarian and triple-negative breast cancer." (PMID 34635660, 2021). "Pathogenic germline mutations in BRCA1, BRCA2, PALB2, RAD51C, and RAD51D, all of which are involved in the HR pathway, are known to confer high or moderate penetrance susceptibility to ovarian and/or triple-negative breast cancer." (PMID 34635660, 2021). "Additionally, single P/LP germline variants in the PTEN and RAD51C genes, as well as a somatic variant in PALB2, were associated with triple-negative breast cancer." (PMID 40710012, 2025).
serous ovarian cancer (10 papers, 2011 to 2025). "Clinically, immunostaining of high-grade serous ovarian cancer showed higher levels of RAD51C protein compared to benign tumors, and increased RAD51C levels were associated with higher clinical staging and poorer prognosis." (PMID 35626165, 2022). "Another RAD51C truncating variant was a splice-site alteration, c.1026+5_1026+7delGTA, identified in a patient who developed endometrial carcinoma seven years after a diagnosis of ovarian serous adenocarcinoma." (PMID 26057125, 2015). "Approximately 50% of high-grade serous ovarian cancers are characterized by HR deficiency, which involves mutations in BRCA1/2, the MRN complex (MRE11, RAD50, NBS1), ATM, RAD51C/D, PALB2, BRIP1, BARD1, and other genes." (PMID 31572446, 2019). "Similarly, a recent study in high-grade serous ovarian carcinoma showed that homozygous methylation of the RAD51C promoter is predictive of sensitivity to PARP inhibition." (PMID 39695768, 2024). "For example, susceptibility to high-grade serous ovarian cancer (HGSOC) is driven by mutations in genes that are involved in DNA double strand break repair (BRCA1, BRCA2, BRIP1, RAD51D and RAD51C), and as a consequence these tumors are highly genomically unstable." (PMID 28881617, 2017).
hereditary cancer (8 papers, 2014 to 2023). Malignant neoplasms occurring in families at a rate greater than that expected by chance and caused by germline mutations in a specific gene. "In our analysis one of the BRCA1, BRCA2, RAD51C, and PALB2 mutations was found in 25.8% of familial cancer cases and in 9.9% of non-familial cases, similar to what has been reported previously." (PMID 33670479, 2021).
breast tumors (5 papers, 2011 to 2023). "Previous studies have shown that breast tumours from individuals carrying an LoF mutation in RAD51C accompanied with loss of the wild-type allele were associated with single base substitution mutational signature 31,13." (PMID 35039523, 2022). "Twenty invasive breast tumours and one HGSOC from 21 cases were analysed using whole-exome sequencing (n = 5), Sanger sequencing (n = 2), and/or a targeted sequencing gene panel that included all exons and intron boundaries of RAD51C and other common BC somatically mutated genes (n = 14)." (PMID 35039523, 2022). "Promoter hypermethylation of BRCA1 has been reported in 13% of sporadic breast tumors, with promoter hypermethylation of FANCC (PALB2), FANCO (RAD51C), and FANCF also reported." (PMID 31320901, 2019). "Indeed, the size distribution of deletions and the presence of a few other types of non-clustered rearrangements in RAD51C−/−, XRCC2−/−, XRCC3−/−, BRCA2−/−, or PALB2−/− mutant cells closely resembled the predominant rearrangement signature of BRCA2-deficient breast tumors." (PMID 31727117, 2019).
endometrial cancer (5 papers, 2015 to 2025). Primary or metastatic malignant neoplasm involving the endometrium (mucous membrane that lines the endometrial cavity). "In our study, we observed that one patient with endometrial cancer harboring a deleterious PTEN variant and one patient with metastatic basal cell carcinoma (skin cancer) carrying a deleterious variant of RAD51C responded to olaparib treatment." (PMID 34206535, 2021). "Burden testing identifies 13 cancer genes with significant enrichment of rare truncations, some associated with specific cancers (for example, RAD51C, PALB2 and MSH6 in AML, stomach and endometrial cancers, respectively)." (PMID 26689913, 2015).